FN1 (fibronectin 1)
Diseases named in the same sentence as FN1 in open-access papers (continued):
Sharing a sentence is not in itself a finding about the gene and the disease.
adenocarcinoma (10 papers, 2018 to 2025). A common cancer characterized by the presence of malignant glandular cells. "In the GC sample cohort from the TCGA (Stomach adenocarcinoma (TCGA, Firehose Legacy, n = 478)), the levels of several markers for macrophages (FN1, MRS1, CD68, and CCL7), blood vessels (CDH5) and lymphatic vessels (VEGFC) exhibited positive correlations with TGM2 expression." (PMID 32467608, 2020). "Changes in SERPINE1, CDK1, ZWINT, and FN1 expression were validated using qRT-PCR after HMGB1 silencing or overexpression in PC-3 and LNCaP (selected as an adenocarcinoma model of PCa responding to hormonal treatment) cell lines." (PMID 38542079, 2024).
cardiovascular diseases (8 papers, 2013 to 2026). "From the 42 DASGs-DEGs-overlap genes, we selected Fn1, Fhl1 and Postn for qRT-PCR validation based on the gene expression levels in samples, FC value and correlation with cardiovascular diseases." (PMID 36435743, 2022). "Coagulation is an ongoing process in serum and deficiencies of several proteins, such as protein Z (PROZ), fibronectin 1 (FN1), and gelsolin (GSN), have been identified to be involved in cerebrovascular and cardiovascular diseases." (PMID 27379006, 2016).
colorectal (4 papers, 2015 to 2021). "Furthermore, Fn1 also participates in colorectal carcinogenesis by promotion vascular endothelial proliferation, migration, and invasion." (PMID 34539543, 2021).
neurodegenerative disease (4 papers, 2020 to 2025). A disorder of the central nervous system characterized by gradual and progressive loss of neural tissue and neurologic function. "A notable feature of neurodegenerative diseases is the increase in FN1+ and SPP1+ microglia-like cells, which express risk genes associated with AD and PD." (PMID 40510352, 2025). "Among these, FN1+ microglia cells were found to be particularly elevated in neurodegenerative diseases, suggesting their potential role in disease progression or response." (PMID 40510352, 2025).
connective tissue disorder (3 papers, 2012 to 2023). A disease involving the connective tissue. "Via IPA, Akt was associated with antigen presentation, cell-to-cell signaling and interaction, cellular growth and proliferation; FN1 with connective tissue disorders, genetic disorder and cellular assembly and organization; and NFkB with embryonic development and organismal development." (PMID 22616791, 2012).
head and neck tumors (2 papers, 2017 to 2025). "Furthermore, studies on head and neck tumors have demonstrated that high FN1 expression is significantly associated with poor prognosis and higher pathological grade in HNSCC patients." (PMID 40380260, 2025).
metabolic disease (2 papers, 2017 to 2020). A congenital disorder (due to inherited enzyme abnormality) or acquired (due to failure of a metabolically important organ) disorder resulting from an abnormal metabolic process. "Metabolic disorders further impacted cell death and metastasis, in part by regulating FN1, VTN, ENO2, and VEGFA." (PMID 28211215, 2017).
hematopoietic neoplasms (1 paper, 2025). "However, the role of FN1 in hematopoietic neoplasms remains to be fully elucidated." (PMID 41488007, 2025).
Muscular Disorders (1 paper, 2022). "From twenty genes of “Cellular Development, Cellular Movement, Skeletal and Muscular Disorders”, six DEGs in the top network related to RSK1 KO (TTLL12, ADMA22, FN1, LPAR1, MMP16, and NRN1) were highly correlated with RSK1 expression, with significant R and p values." (PMID 36684450, 2022).
myopathies (1 paper, 2026). "Fibronectin 1, fibrinogen alpha chain, musculoskeletal embryonic nuclear protein 1, glutathione S-transferase 2, calsequestrin-2, and endoplasmin emerged as potential biological markers and their prospective roles in the pathogenesis of these myopathies are discussed." (PMID 42278140, 2026).
FN1 also shares sentences with these, for which no sentence is quoted: Glomerular sclerosis (12 papers); kidney damage (9); astrocytoma (8); chronic kidney disease (8); idiopathic pulmonary fibrosis (7); Insulin resistance (7); ocular hypertension (7); bacterial infection (5); Crohn disease (5); dilated cardiomyopathy (4); fibrosarcoma (4); inflammation (4); multiple myeloma (4); periodontal disease (4); systemic sclerosis (4); breast adenocarcinoma (3); chronic myeloid leukemia (3); dyslipidemia (3); emphysema (3); inflammatory myofibroblastic tumor (3); metastasis (3); multiple sclerosis (3); Neurological disorders (3); parasitic infection (3); Parkinson disease (3); pneumonia (3); sarcoma (3); scleroderma (3); skin squamous cell carcinoma (3); thrombosis (3).
A further 211 diseases each share a sentence with FN1 in 3 papers or fewer.